VANGL2 (VANGL planar cell polarity protein 2)
Diseases named in the same sentence as VANGL2 in open-access papers (continued):
Sharing a sentence is not in itself a finding about the gene and the disease.
neuroblastoma (3 papers, 2015 to 2019). Neuroblastoma (NB) is the most common solid, extracranial childhood tumor. "Here we show that high expression of the PCP core genes Prickle1 and Vangl2 is associated with low-risk neuroblastoma, suppression of neuroblastoma cell growth and decreased Wnt/β-catenin signaling." (PMID 27036398, 2016). "High expression of Prickle1 and Vangl2 corresponded to better survival and low-risk disease across different neuroblastoma expression array datasets." (PMID 27036398, 2016). "This was also evident from analysis of expression arrays of primary neuroblastoma where high expression of Prickle1 and Vangl2 mRNA are significantly coupled to low-risk disease and good patient survival." (PMID 27036398, 2016). "Previous studies have demonstrated that the expression of VANGL2 is significantly downregulated in several cancer cell lines and primary tumors, and a low expression of VANGL2 is associated with a significantly worse clinical outcome in neuroblastoma." (PMID 25352048, 2015). "High expression level of PRICKLE1 and VANGL2 correlates with low risk of neuroblastoma." (PMID 31569501, 2019). "Further studies showed that the core WNT/PCP signaling components PRICKLE1 and VANGL2 directly inhibit canonical WNT signaling in neuroblastoma cells." (PMID 31569501, 2019). "Our experimental data demonstrate that high expression of Prickle1 and Vangl2 reduce the growth of neuroblastoma cells and indicate different roles of PCP proteins in tumorigenic cells compared to normal cells." (PMID 27036398, 2016). "Overexpression of Prickle1 or Vangl2 was coupled to decreased neuroblastoma growth and reduced expression of active β-catenin." (PMID 27036398, 2016). "Genetic knock-down of the core PCP genes Prickle1 or Vangl2 resulted in increased growth of neuroblastoma cells and increased active β-catenin levels, while overexpression had the opposite effect." (PMID 27036398, 2016). "We analyzed neuroblastoma expression cohorts and show that high expression of the PCP proteins Prickle1 and Vangl2 correlates with low-risk disease and patient survival." (PMID 27036398, 2016). "High expression of the PCP core proteins Prickle1 and Vangl2 reduce the growth of neuroblastoma cells and correspond to low-stage disease and patient survival." (PMID 27036398, 2016). "In contrast to neuroblastoma cells, siRNA against Vangl2 decreased the cell number in C17.2 compared to siRNA control (75 %)." (PMID 27036398, 2016). "Next, we investigated the level of the PCP core proteins Prickle1 and Vangl2 in neuroblastoma cells." (PMID 27036398, 2016). "Protein expression of Prickle1 and Vangl2 were detected in all tested neuroblastoma cell lines." (PMID 27036398, 2016). "Knockdown of Prickle1 or Vangl2 induced a significant increase in TOPFlash luciferase reporter activity i.e. β-catenin transcriptional activity, compared to siRNA control transfected neuroblastoma cells." (PMID 27036398, 2016). "Overexpression of Prickle1 or Vangl2 significantly inhibited neuroblastoma cell growth compared to cDNA control transfected cells in SK-N-AS (Prickle1 26 % and Vangl2 44 %), SH-EP1 (Prickle1 38 % and Vangl2 60 %), SK-N-BE (Prickle1 53 % and Vangl2 58 %) and SK-N-DZ (Prickle1 83 % and Vangl2 94 %)." (PMID 27036398, 2016). "The observation in our study, that high expression of the PCP proteins Prickle1 or Vangl2 reduces the growth of neuroblastoma cells, further supports the notion that key proteins within the PCP signaling pathway may act as tumor suppressors." (PMID 27036398, 2016). "Additionally, siRNA experiments have revealed that knock down of VANGL2 increases cell proliferation of neuroblastoma cells." (PMID 25352048, 2015). "In contrast to neuroblastoma cells, both non-tumorigenic neural cells and transgenic mouse embryos with overexpression of Vangl2 in nestin-expressing cells showed increased active β-catenin and reduced differentiation." (PMID 27036398, 2016).
neuroblastoma (continued). "Transfections with cDNA plasmids or siRNA were used to increase and suppress Prickle1 and Vangl2 expression in neuroblastoma cells and in non-tumorigenic cells." (PMID 27036398, 2016).
Sepsis (3 papers, 2024 to 2025). Sepsis is defined as life-threatening organ dysfunction caused by a dysregulated host response to infection. "Here, we report that Vangl2 is upregulated in patients with sepsis and identify Vangl2 as a negative regulator of The nuclear factor-kappaB (NF-κB) signaling by regulating the protein stability and activation of the core transcription component p65." (PMID 39269442, 2024). "To determine the function of Vangl2 during LPS-induced sepsis, we specifically ablated Vangl2 in myeloid cells by crossing Vangl2flox/flox mice with mice expressing lysozyme proximal promoter (Lyz2-Cre)." (PMID 39269442, 2024). "(A) Transcription levels of Vangl2 in PBMCs from healthy volunteers (healthy control, HC) and sepsis patients were analyzed by real-time PCR (n = 8)." (PMID 39269442, 2024). "To investigate the mechanisms by which Vangl2 prevents sepsis, we performed RNA-seq analysis to identify signal pathways involved in LPS-induced septic shock by comparing LPS-stimulated BMDMs from Vangl2ΔM and WT mice." (PMID 39269442, 2024). "Expression of Vangl2 from database GSE156382 also confirmed that Vangl2 mRNA was induced during sepsis." (PMID 39269442, 2024). "In addition to its developmental function, our recent studies indicate that VANGL2 can also modulate anti-viral immunity and sepsis progression, broadening its role in regulating immune responses." (PMID 39899477, 2025). "However, the latest research has found that in the lipopolysaccharide (LPS)-induced sepsis model, van Gogh-like protein 2 (VANGL2) recruits PDZ and lim domain protein 2 (PDLIM2) to catalyze the K63-type ubiquitination of p65." (PMID 40643532, 2025). "We recently explored the function of VANGL2 in anti-viral infection and sepsis." (PMID 39899477, 2025). "In this study, we uncover a previously unrecognized role of Vangl2, as a ‘molecular brake’, in the negative regulation of NF-κB signaling to prevent excessive and potentially harmful immune responses during sepsis in both human patient samples and LPS-induced mouse model." (PMID 39269442, 2024). "To investigate the potential role of Vangl2 in inflammatory response, we first analyzed the expression of Vangl2 in peripheral blood mononuclear cells (PBMCs) from sepsis patients and found mRNA level of Vangl2 was increased in the sepsis patients compared to healthy control." (PMID 39269442, 2024). "In detail, Vangl2 functions as an adaptor protein to recruit an E3 ubiquitin ligase PDLIM2 to increase K63-linked ubiquitination of p65 and promotes NDP52-mediated p65 degradation through selective autophagy, resulting in ameliorating sepsis and suppressing production of proinflammatory cytokines." (PMID 39269442, 2024). "In addition, the present study showed that Vangl2 prevented the progression of sepsis and the accumulation of inflammatory cytokines through suppressing NF-κB pathway: Vangl2 inhibited LPS-induced NF-κB activation by delivering p65 to autophagosome for degradation." (PMID 39269442, 2024).
Strabismus (3 papers, 2013 to 2021). A misalignment of the eyes so that the visual axes deviate from bifoveal fixation. "Vangl1 is a highly conserved, structurally similar paralogue of Vangl2, and is the only other known mammalian orthologue of Drosophila strabismus/Van Gogh." (PMID 25264362, 2015). "Subsequently, CK1δ/ε activates Vangl2 by phosphorylation, similarly CK1 phosphorylates Vangl2/strabismus in Drosophila22." (PMID 33824332, 2021).
chronic lymphocytic leukaemia (2 papers, 2016 to 2024). "VANGL2 upregulated in B lymphocytes of chronic lymphocytic leukaemia (CLL) patients, and levels of Wnt/PCP-related proteins accumulate in the late stage of the disease, indicating the crucial role of Wnt/PCP pathway in CLL cell migration and transendothelial invasion." (PMID 39871948, 2024). "Chronic lymphocytic leukemia (CCL) cells are induced to migrate by Wnt5a in a chemokine gradient manner, which is important in regulating chemotaxis and trans-endothelial migration of CLL cells, apparently through upregulating PCP components including Vangl2, Prickle1, CK1ε, Dvl, and Celsr1." (PMID 27571105, 2016).
colon cancer (2 papers, 2018 to 2024). "Recent clinical studies have demonstrated that Vangl2 is frequently silenced by promoter hypermethylation in colon cancer cell lines and tumor samples." (PMID 30532125, 2018). "ROR2, VANGL2, and DVLs were demonstrated to be involved in the WNT pathway, serving as pivotal regulators of proliferation, metastasis, and development of colon cancer, thyroid cancer, and melanoma." (PMID 39052013, 2024).
Diabetes (2 papers, 2017 to 2025). "Diabetes also affects testicular VANGL planar cell polarity protein 2 (VANGL2), a protein in the apical ectoplasmic specialization (ES), as well as steroid receptor coactivator (Src) and focal adhesion kinase (FAK) activation." (PMID 41158715, 2025). "In addition, WNT5A expression levels in VAT correlated with those of some of the PCP signaling components, such as VANGL2, PRICKLE1, DSH1,2,3 and DIVERSIN/ANKRD6 only in subjects with diabetes." (PMID 29229927, 2017). "Expression levels of ROR2, FZD7, VANGL2 and PRICKLE1 correlated with each other, and these correlations were statistically significant in subjects with and without diabetes, although in most cases they were much stronger in the group with diabetes." (PMID 29229927, 2017). "Specifically, VAT expression of ROR2, FZD7, VANGL2 and PRICKLE1 correlated with that of DSH1,2,3 and DIVERSIN/ANKRD6 in the diabetes group, but not in most cases in the group without diabetes." (PMID 29229927, 2017).
focal segmental glomerulosclerosis (2 papers, 2018 to 2023). A renal disorder characterized by sclerotic lesions in the glomeruli. "VANGL2 transcripts levels were increased in the glomeruli of individuals with focal segmental glomerulosclerosis." (PMID 37035301, 2023).
gastric cancer (2 papers, 2017 to 2021). A primary or metastatic malignant neoplasm involving the stomach. "In zebrafish epiblast cells, mouse intestinal telocytes and human gastric cancer cells, Vangl2 activation generates extremely long cytonemes, which branch and deliver Wnt protein to multiple cells." (PMID 33824332, 2021). "As there is no suitable antibody for immunohistochemistry against zebrafish Vangl2 available, we stained the Wnt signaling active gastric cancer cells AGS with a human anti-Vangl2 antibody and, indeed, could find that endogenous hVangl2 is also localized to the tip of filopodia of AGS cells." (PMID 33824332, 2021). "Our results indicated that several EBV genes, LMP-1, BALF1, BALF2, BALF4 and BALF5, may interact with the expression of human GC genes, e.g., the CNTD2 and VANGL2, and the gastric cancer-related pathways, e.g., Jak-STAT signaling and phosphatidylinositol signaling system." (PMID 28415594, 2017). "In addition, we show that human gastric cancer cells AGS process paracrine Wnt signaling via cytonemes, which are influenced by Vangl2 activity." (PMID 33824332, 2021).
glioblastoma (2 papers, 2024 to 2025). The most malignant astrocytic tumor (WHO grade IV). "It was observed that VANGL1 and VANGL2 are highly up-regulated in glioblastoma (GBM) progression and promote cell invasion and migration." (PMID 41385185, 2025). "We identified substantial upregulation of VANGL2 gene in both low-grade glioma (LGG) and glioblastoma (GBM)." (PMID 39871948, 2024).
Hydrocephalus (2 papers, 2016 to 2021). Hydrocephalus is an active distension of the ventricular system of the brain resulting from inadequate passage of CSF from its point of production within the cerebral ventricles to its point of absorption into the systemic circulation. "Thus, and largely based on the great similarity between the NHERF1 and Celsr knockout phenotypes, we propose that the hydrocephalus phenotype of the NHERF1-/- mouse is caused primarily by defective PCP resulting from the mislocalization of Vangl2 in the ependyma." (PMID 27055101, 2016).
melanoma (2 papers, 2023 to 2024). A malignant, usually aggressive tumor composed of atypical, neoplastic melanocytes. "In melanoma, RNF43 has been found to inhibit cell invasion and reverse the resistance to BRAF V600E and MEK inhibitors by stimulating the ubiquitination and proteasomal degradation of VANGL2 and inhibiting ROR2 in vitro and in vivo." (PMID 37848933, 2023).
nephritis (2 papers, 2016 to 2018). Inflammation of renal tissue. "Furthermore, podocyte-specific deletion of Vangl2 exaggerated the severity of the nephrotoxic nephritis model with enhanced glomerulosclerosis." (PMID 27597235, 2016).
osteosarcoma (2 papers, 2015 to 2018). A usually aggressive malignant bone-forming mesenchymal neoplasm, predominantly affecting adolescents and young adults. "VANGL2 has been proved to be structurally associated with the Wnt pathway, and to be implicated in the development of osteosarcomas." (PMID 25352048, 2015). "In conclusion, the results of the present study indicated that miR-542-3p may function as an oncogene by targeting VANGL2 during osteosarcoma pathogenesis." (PMID 25352048, 2015). "However, miR‐542‐3p may function as an oncogene by targeting VANGL2 during osteosarcoma pathogenesis (Li, Liu, Pei, Wang, & Lv, 2015)." (PMID 29319176, 2018). "However, as a target gene of miR-542-3p, whether the osteosarcoma cell proliferation and migration mediated by VANGL2 are regulated by miR-542-3p has remained elusive." (PMID 25352048, 2015).
uterine cancer (2 papers, 2020 to 2024). Primary or metastatic malignant neoplasm involving the uterine corpus and/or the cervix. "The results of the CPTAC dataset showed higher expression of VANGL2 total protein in the primary tissues of brain cancer, LUSC, uterine cancer (p < 0.0001) and ovarian cancer (p < 0.001) than in normal tissues." (PMID 39871948, 2024).
viral infection (2 papers, 2023 to 2025). "In general, these results suggest that IFN-induced VANGL2 during virus infection effectively inhibits IFN-I signaling and antiviral immunity." (PMID 37352355, 2023). "Last, to further determine the role of VANGL2 in host defense against viral infection in vivo, we infected the control and Vangl2-CKO mice using VSV by intraperitoneal injection." (PMID 37352355, 2023). "VANGL2 could be a potential clinical therapeutic target for viral infectious diseases, including COVID-19." (PMID 37352355, 2023). "In general, these findings revealed a negative feedback loop of IFN-I signaling through the VANGL2-TRIP-TBK1-OPTN axis and highlighted the cross-talk between IFN-I and autophagy in preventing viral infection." (PMID 37352355, 2023).
acute myeloid leukaemia (1 paper, 2024). "Meanwhile, VANGL2 expression was significantly lower in kidney chromophobe (KICH), kidney renal clear cell carcinoma (KIRC), acute myeloid leukaemia (LAML), and skin cutaneous melanoma (SKCM) (p < 0.001) than in their respective adjacent normal tissues." (PMID 39871948, 2024).
Anxiety (1 paper, 2022). Intense feelings of nervousness, tension, or panic often arise in response to interpersonal stresses. "Adult neurogenesis has been widely associated with anxiety-related behaviors and spatial learning and memory capabilities so we analyzed the consequences of Vangl2 mutation on both affective and cognitive functions." (PMID 35370613, 2022).
autoimmune disease (1 paper, 2024). A disorder resulting from loss of function or tissue destruction of an organ or multiple organs, arising from humoral or cellular immune responses of the individual to their own tissue constituents. "Vangl2-mediated downstream factors of Toll-like (TLR) or interleukin (IL)-1 receptor, such as myeloid differentiation factor 88 (MyD88), suggesting that Vangl2 may play roles in immune-related diseases, including autoimmune diseases." (PMID 39269442, 2024).
Bardet-Biedl syndrome (1 paper, 2009). A ciliopathy with multisystem involvement. "In the kidney Vangl2 genetically interacts with Bardet-Biedl syndrome (BBS) genes." (PMID 19439065, 2009).
colitis (1 paper, 2025). Inflammation of the colon. "Myeloid VANGL2 deficiency exacerbates the progression of DSS-induced colitis in mice and specifically enhances the activation of NLRP3 inflammasome in macrophages." (PMID 39899477, 2025). "NLRP3-specific inhibitor MCC950 effectively alleviates DSS-induced colitis in VANGL2 deficient mice." (PMID 39899477, 2025). "Myeloid Vangl2-deficiency in mice results in increased susceptibility to DSS-induced colitis due to the overactivation of NLRP3 inflammasome." (PMID 39899477, 2025). "Moreover, NLRP3 inhibitor MCC950 effectively reversed the exacerbation of colitis triggered by Vangl2 deficiency." (PMID 39899477, 2025). "Based on our findings, we propose a working model to illustrate how VANGL2 plays a protective role in colitis." (PMID 39899477, 2025). "Taken together, these data suggest that VANGL2 alleviates the progression of DSS-induced colitis in mice by blocking the NLRP3 inflammasome activation." (PMID 39899477, 2025). "In this study, we show that VANGL2 is down-regulated in human and mouse colitis and negatively correlated with the progression of IBD." (PMID 39899477, 2025). "We found that the mRNA level and protein level of VANGL2 in colon were decreased in mice with DSS-induced colitis." (PMID 39899477, 2025). "We next investigated whether VANGL2 affects inflammasome activation in mice with DSS-induced colitis." (PMID 39899477, 2025). "Therefore, VANGL2 negatively regulates the inflammasome activation in mice with DSS-induced colitis." (PMID 39899477, 2025). "Furthermore, March8-WT and March8-W110A chimeric mice were constructed to investigate the effect of VANGL2 on the progression of DSS-induced colitis." (PMID 39899477, 2025). "Myeloid knockout of Vangl2 enhances the activation of NLRP3 inflammasome and exacerbates the progression of DSS-induced colitis in mice." (PMID 39899477, 2025). "Here, we demonstrate the role and regulatory mechanism of VANGL2 in IBD patients and DSS-induced colitis in mice." (PMID 39899477, 2025). "Subsequently, we established a DSS-induced acute colitis model in C57BL/6 wild-type (WT) mice and traced the change of VANGL2 expression." (PMID 39899477, 2025). "Taken together, we identified VANGL2 as a negative regulator of NLRP3 inflammasome and involved in regulating the pathogenesis of DSS-induced colitis." (PMID 39899477, 2025). "VANGL2 decreases in IBD patients and dextran sulfate sodium (DSS)-induced colitis in mice." (PMID 39899477, 2025). "Notably, knockdown of VANGL2 or MARCH8 effectively enhanced NLRP3 inflammasome activation in PBMCs from healthy individuals, but not from IBD patients, which strongly suggest a role for VANGL2 in anti-colitis progression via the NLRP3 inflammasome pathway." (PMID 39899477, 2025). "The results showed that VANGL2 did not affect NLRP3 inflammasome activation and colitis progression in March8-W110A mice compared to March8-WT mice." (PMID 39899477, 2025). "Furthermore, VANGL2 did not affect the phosphorylation of p65 and IκBα in mice with DSS-induced colitis." (PMID 39899477, 2025).
colorectal cancer (1 paper, 2025). A primary or metastatic malignant neoplasm that affects the colon or rectum. "In particular, Vangl2 has been shown to promote the migration and invasion of colorectal cancer cells by activating the fibronectin/integrin β1/FAK signaling cascade through DVL2." (PMID 41425715, 2025).
congenital heart disease (1 paper, 2024). A heart disease that is present at birth. "Here we report three new families with missense variants in VANGL2 associated with heterotaxy and congenital heart disease p.(Arg169His), non-syndromic hearing loss p.(Glu465Ala) and congenital heart disease with brain defects p.(Arg135Trp)." (PMID 37815931, 2024).